RNU7-38P (RNA, U7 small nuclear 38 pseudogene)
Synonyms: U7.38
Gene: Small nuclear RNA gene on chromosome 10 (71,844,735 to 71,844,794, reverse strand). Ensembl gene ENSG00000238446.
Homologues: Orthologues: chimpanzee U7 (100% identical), macaque U7 (97% identical). Paralogues in human: RNU7-2P (88% identical), RNU7-3P (88% identical), RNU7-4P (88% identical), RNU7-7P (88% identical), RNU7-1 (87% identical), RNU7-11P (87% identical), RNU7-14P (87% identical), RNU7-8P (87% identical), RNU7-10P (85% identical), RNU7-19P (85% identical), RNU7-20P (85% identical), RNU7-25P (85% identical), and 142 more.